CEP295 (centrosomal protein 295)
Description:
Centriole-enriched microtubule-binding protein involved in centriole biogenesis. Essential for the generation of the distal portion of new-born centrioles in a CPAP- and CEP120-mediated elongation dependent manner during the cell cycle S/G2 phase after formation of the initiating cartwheel structure. Required for the recruitment of centriolar proteins, such as POC1B, POC5 and CEP135, into the distal portion of centrioles. Also required for centriole-to-centrosome conversion during mitotic progression, but is dispensable for cartwheel removal or centriole disengagement. Binds to and stabilizes centriolar microtubule. May be involved in ciliogenesis.
Synonyms: KIAA1731; SCKL11
Tractability: PROTAC: ubiquitination databases record sites on it.
Gene: Protein-coding gene on chromosome 11 (93,661,682 to 93,730,358, forward strand). Ensembl gene ENSG00000166004.
Subcellular location: Cytoplasm, cytoskeleton, microtubule organizing center, centrosome, centriole; Cytoplasm, cytoskeleton, microtubule organizing center, centrosome; Cytoplasm, cytoskeleton, spindle; Cytoplasm, cytoskeleton
Gene Ontology:
Molecular function: microtubule binding
Biological process: centriole replication; positive regulation of centriole elongation; positive regulation of centrosome duplication; positive regulation of establishment of protein localization; positive regulation of protein acetylation; regulation of centriole replication
Cellular component: centriole; centrosome; cytoplasm; cytoskeleton; mitotic spindle microtubule; cytosol; spindle
Genetic constraint (gnomAD): Loss-of-function variants: 146 observed, 227.83 expected, observed/expected ratio (o/e) 0.64, 90% interval 0.56 to 0.74. The upper end of that interval is the gene's LOEUF score, 0.74, which puts it in group 3 of 6, group 1 being the genes least tolerant of losing a copy. Missense variants: 2,407 observed, 2,562.7 expected, observed/expected ratio (o/e) 0.94, 90% interval 0.91 to 0.97. Synonymous variants: 844 observed, 922.07 expected, observed/expected ratio (o/e) 0.92, 90% interval 0.86 to 0.97.
Homologues: Orthologues: chimpanzee CEP295 (98% identical), macaque CEP295 (94% identical), guinea pig CEP295 (70% identical), dog CEP295 (69% identical), pig CEP295 (69% identical), rabbit CEP295 (68% identical), mouse Cep295 (58% identical), rat Cep295 (57% identical), zebrafish alms1 (6% identical). Paralogues in human: ALMS1 (12% identical), CEP295NL (7% identical), C10orf90 (4% identical).
Diseases named in the same sentence as CEP295 in open-access papers:
CEP295 is named in the same sentence as 5 diseases in open-access papers, as found by Europe PMC text mining. Sharing a sentence is not in itself a finding about the gene and the disease. The quoted sentences say what the papers report.
cancer (1 paper, 2024). A tumor composed of atypical neoplastic, often pleomorphic cells that invade other tissues. "CDC20B, DCTN3, CEP295 and TIMLESS were shown to promote cell cycle progression and be associated with tumor progression in many types of cancer." (PMID 39527598, 2024).
CEP295 also shares sentences with these, for which no sentence is quoted: glaucoma (1 paper); lung carcinoma (1); Obesity (1); tumor (1).